STC1 (stanniocalcin 1)
Diseases named in the same sentence as STC1 in open-access papers (continued):
Sharing a sentence is not in itself a finding about the gene and the disease.
melanoma (10 papers, 2009 to 2025). A malignant, usually aggressive tumor composed of atypical, neoplastic melanocytes. "Other ARGs, including OLR1, KCNJ8, APP, POSTN, and STC1 showed significant yet heterogenous relationships with immune cells subsets, reinforcing the complexity of immune regulation in melanoma." (PMID 40943183, 2025). "In melanoma, STC1 drives tumor progression by competitively binding to betaPIX, leading to the nuclear translocation of YAP and recruitment of M2 macrophages." (PMID 39668832, 2024). "The histone H3 lysine 27 (H3K27) demethylase JMJD3 up‐regulates STC1 expression, activates NF‐κB and PI3K pathways and promotes distant metastasis of melanoma, indicating that a high STC1 expression level is related to metastasis." (PMID 32468698, 2020). "JMJD3, a kind of histone demethylase that correlates with melanoma growth and metastasis, also up‐regulates STC1 expression." (PMID 32468698, 2020). "JMJD3 also confered self-renewal ability in melanoma cells by up-regulating expression of stanniocalcin-1 (STC1) via NF-κB pathway." (PMID 31701394, 2019). "In melanoma (MEL), STC1 had a positive relationship with inflammation, angiogenesis, EMT, metastasis, quiescence, hypoxia, and apoptosis." (PMID 39201771, 2024).
prostate carcinoma (9 papers, 2005 to 2025). A carcinoma that arises from epithelial cells of the prostate gland. "In this work, the electronic tongue concept with an array of sensors prepared with thin films of STC1 antibodies from a fish was used to develop a sensorial device to detect STC1 antigen and, possibly, prostate cancer in the future." (PMID 37998156, 2023). "In this work, we developed a prototype of an electronic tongue based on thin films of Stanniocalcin-1 protein antibodies to diagnose prostate cancer." (PMID 37998156, 2023). "In this work, an electronic tongue (ET) prototype, based on a set of four sensors prepared from thin films that included STC1 antibodies for detecting prostate cancer, was developed." (PMID 37998156, 2023). "Recent studies revealed that the secretion of glycoprotein stanniocalcin-1 (STC1) is associated with the development and progression of different types of malignant tumors, an observation that has led to the proposal that it could be used as a tumor marker for prostate cancer." (PMID 37998156, 2023). "STC1 expression is, however, much reduced in prostate cancer cell lines and xenografts." (PMID 34911496, 2021). "Of note, multiple genes hitherto known to be associated with prostate cancer progression were observed in the top list of upregulated entities including but not limited to MYBL2, ESM1, PBK, and UBE2C in PC3, and MMP1, CCL5, and STC1 in DU145." (PMID 31493351, 2019). "Here we show that miR-101 targets other known players in prostate cancer DDIT4, STC1 and QK1." (PMID 27270442, 2016). "It is interesting to note that the prostate cancer cell lines, PC3 and C4-2, analyzed expressed STC1 (but not PENK), and it is thus possible that STC1 expression could be contributed by epithelial cells as well." (PMID 16343351, 2005).
bladder cancer (8 papers, 2016 to 2025). "A recent study reveals that STC1 is a novel biomarker associated with immune characteristics and prognosis of bladder cancer and also inhibits APC phagocytosis, contributes to tumor immune evasion and immunotherapy resistance." (PMID 35607443, 2022). "We discovered that up-regulating miR-130b-3p was negatively associated with PTEN and stanniocalcin 1 (STC1) in clinical bladder cancer specimens." (PMID 28042869, 2016). "A study illustrated that STC1 is highly expressed in bladder cancer, enhances PD‐L1 expression, and increases the degree of T cell immune infiltration." (PMID 35403268, 2022). "The results showed that the two target genes were both associated with bladder cancer, and PTEN showed a higher correlation than STC1." (PMID 28042869, 2016).
leukemia (8 papers, 2012 to 2025). A malignant (clonal) hematologic disorder, involving hematopoietic stem cells and characterized by the presence of primitive or atypical myeloid or lymphoid cells in the bone marrow and the blood. "In addition, STC1 is associated with relapse in leukaemia patients." (PMID 32468698, 2020). "A study using TriCEPS-based ligand–receptor methodology and surface plasmon resonance assays identified that human stanniocalcin-1 binds to insulin-like growth factor-2 receptors in human leukemia monocytic cells with high affinity." (PMID 35798563, 2022). "In this study, we used the TriCEPS-based ligand–receptor methodology to identify the putative binding proteins of human STC1 (hSTC1) in the human leukemia monocytic cell line, ThP-1." (PMID 35798563, 2022). "In an earlier report, STC‐1 expression was recognized in 8 of 10 leukemia cell lines." (PMID 33826244, 2021). "Furthermore, some leukemia cell lines express STC‐1, and it has been shown that STC‐1 mRNA levels in peripheral blood correlate with the risk of disease recurrence after chemotherapy." (PMID 33826244, 2021). "Upregulation of hypoxia-regulated factors occurred rapidly in MSCs when cocultured with AML, but this is not maintained after leukemia cells are withdrawn from the culture, potentially explaining why STC1 and HIF-1α have not been identified in AML patient–derived MSCs." (PMID 32364536, 2020).
lung adenocarcinoma (8 papers, 2017 to 2025). A carcinoma that arises from the lung and is characterized by the presence of malignant glandular epithelial cells. "identify the fibroblast-derived, secreted glycoprotein STC1 as a paracrine regulator of tumor-associated macrophage differentiation in lung adenocarcinoma." (PMID 32579928, 2020). "Moreover, STC1, a ubiquitin-related gene, is significantly upregulated in lung adenocarcinoma and is associated with poor prognosis, suggesting its potential as a biomarker for prognosis evaluation, tumor characterization, and therapeutic decision-making." (PMID 40777122, 2025). "Fibroblast-derived STC1 regulates tumor-associated macrophages and lung adenocarcinoma development." (PMID 37400459, 2023). "Because intra-tracheal delivery of STC1 protein into a mouse lung fibrosis model has been shown to improve the pathology, it would be worthwhile to test a similar strategy for treating lung adenocarcinoma associated with the desmoplastic stroma." (PMID 32579928, 2020). "In human lung adenocarcinomas, STC1 gene expression is well correlated with STC2, suggesting that STC1/2 is expressed by similar cell types." (PMID 32579928, 2020). "Consistent with the mouse data, in human lung adenocarcinoma, STC1 expression is restricted to myofibroblasts, and a significant increase of naive macrophages is detected in STC1-high compared with STC1-low cases." (PMID 32579928, 2020). "The human STC1 gene is located on the short arm of chromosome 8, a region frequently deleted in lung adenocarcinoma, but any tumor-suppressor functions of STC1 in this cancer type has not yet been examined." (PMID 32579928, 2020). "Our analysis of human lung adenocarcinomas is consistent with the myofibroblast-restricted expression of STC1 and a role in TAM modulation." (PMID 32579928, 2020). "In this report, we identified fibroblast-derived STC1 as a key paracrine modulator of the TME in lung adenocarcinoma." (PMID 32579928, 2020). "We have also investigated STC1 expression in human lung adenocarcinoma." (PMID 32579928, 2020). "In human lung adenocarcinomas, we found that STC1 is expressed in only a few αSMA+ cells, suggesting it may be a specific sub-population of phenotypically and functionally heterogeneous TAFs." (PMID 32579928, 2020). "The amplified products were subjected to agarose gel electrophoresis, and six samples all gave clear bands in the correct region indicated by the marker, confirming that the six predicted six-HRGs (STC1, PFKL, HK1, PDK3, SLC2A1, XPNPEP1) were all expressed in lung adenocarcinoma A549 cells." (PMID 37576511, 2023). "To investigate whether STC1 operates in a similar way in human lung adenocarcinoma, we first examined STC1 expression by in situ hybridization (ISH) and detected STC1-expressing cells sporadically in the TME." (PMID 32579928, 2020).
pulmonary fibrosis (7 papers, 2019 to 2023). Chronic progressive interstitial lung disorder characterized by the replacement of the lung tissue by connective tissue, leading to progressive dyspnea, respiratory failure, or right heart failure. "In addition to aging, MMP1 is a biomarker for several cancers, pulmonary fibrosis and potentially Alzheimer’s disease, whereas STC1 is a diagnostic and prognostic biomarker for cancers, pulmonary fibrosis, renal ischemia/reperfusion injury and Alzheimer’s disease." (PMID 33210602, 2020). "MSC-releasing STC1 play an important role in treating several ROS-induced diseases, including retinal degeneration, obesity-induced hepatitis, and lung fibrosis." (PMID 36113772, 2022). "Such a paracrine function of STC1 is analogous to the previously documented paracrine function of mesenchymal stem cell (MSC)-derived STC1 that inhibits lung fibrosis by suppressing TGF-β1 production." (PMID 32579928, 2020). "Interestingly, in a murine model of bleomycin (BLM)-induced lung fibrosis, MSCs were demonstrated to refine the epithelial-mesenchymal transition through secreting mitochondria-related hormone stanniocalcin-1 (STC1), a survival factor." (PMID 37605719, 2023). "Stanniocalcin 1 is a glycoprotein that acts in a paracrine and autocrine fashion to maintain phosphate and calcium metabolism and is usually overexpressed in tumoral tissues and during lung fibrosis." (PMID 34777248, 2021). "In two separate studies, STC1 mediates the anti-apoptotic effects of MSCs in lung epithelial cells, and MSCs exhibited anti-fibrotic impact via STC1 secretion in pulmonary fibrosis, which manifests paracrine function by the reduction in TGF-β1 production from alveolar macrophages." (PMID 31212896, 2019). "Their result showed that STC1 exerted anti-fibrotic effects by diminishing endoplasmic reticulum (ER) and oxidative stress and decreasing TGF-β1 production and collagen-synthesis in the BLM-induced pulmonary fibrosis model." (PMID 37605719, 2023).
Alzheimer disease (5 papers, 2020 to 2023). A progressive, neurodegenerative disease characterized by loss of function and death of nerve cells in several areas of the brain leading to loss of cognitive function such as memory and language. "Intriguingly, a previous study discovered that STC1 concentration was decreased in patients with dementia relative to those Alzheimer's disease and cognitively normal controls." (PMID 34194345, 2021). "Moreover, OA suppressed oxidative stress by regulating the stanniocalcin-1 pathway in a cell model of Alzheimer’s disease treatment, as well as repressed oxidative stress via the SIRT3/NF-κB axis in an in vitro osteoarthritis cell model." (PMID 35056059, 2021). "In Alzheimer's disease, oleanolic acid regulates UCP2 expression via STC-1 to attenuate oxidative stress and β-amyloid levels in N2a/APP695swe cells." (PMID 38127054, 2023).
Cerebral ischemia (5 papers, 2012 to 2024). Restriction of arterial blood supply to the brain associated with insufficient oxygenation to support the metabolic requirements of the tissue. "STC1 is a secreted hormone with antioxidant effects and it has been observed to reduce brain dysfunction after cerebral ischemia/reperfusion by decreasing BBB permeability and oxidative stress parameters." (PMID 37378751, 2024). "In mammals, STC-1 appears to play multiple roles in a series of biological processes, including pregnancy, lactation, angiogenesis, cerebral ischemia, oxidative stress and apoptosis." (PMID 22537917, 2012). "Recently, it has been shown in an animal model of stroke that STC-1 can exert its antioxidant activity by inhibiting brain edema and BBB permeability and consequently improving the neurological alterations following cerebral ischemia." (PMID 33362697, 2020). "Also, STC1 was found to increase the activity of SOD and CAT in the hippocampus of a cerebral ischemia/reperfusion rat model, thereby reducing oxidative stress and blood brain barrier permeability to ameliorate cerebral ischemia, which was consistent with our findings." (PMID 34194345, 2021).
diabetes (5 papers, 2019 to 2025). "Different methylation of Stc1 was one of the genome sites influenced by maternal diabetes during pregnancy, which was associated with impaired insulin secretion and higher risk of T2DM." (PMID 31379744, 2019). "In line with this, overexpression of STC1 in diabetes patients suffering from kidney complications (diabetic-linked kidney disease) would ameliorate further complications due to the protective role of STC1 against oxidative stress and cell apoptosis." (PMID 41155293, 2025). "MSCs treatment attenuated the expression of ICAM1 and VCAM1 in the aortic endothelium, which was enhanced by diabetes;however, the anti-inflammatory phenotype of MSCs was abolished when STC1 was knocked down." (PMID 41249792, 2025). "Given that STC1 colocalizes with insulin in beta-cells, its suitability as a diabetes marker has been considered." (PMID 38712328, 2024). "Moreover, STC-1 expression was decreased in tumors obtained from obese women (p = 0.014) and in women with diabetes mellitus type 2 (DMT2; p = 0.001)." (PMID 34650342, 2021). "Conversely, we observed an increase in STC1 expression in thrombotic patients suffering hyperglycemia, which may be indicative of the progression of diabetes illness, which is often complicated by platelet hyperactivation and, subsequently, the thrombotic events associated with diabetes." (PMID 41155293, 2025). "Stanniocalcins are expressed in the pancreatic islets, where STC1 colocalizes with insulin in beta-cells and STC2 with glucagon in alpha-cells, where they are suggested to exert effects on glucose homeostasis and to be markers of the appearance and progression of diabetes." (PMID 38712328, 2024).
heart failure (5 papers, 2012 to 2021). Inability of the heart to pump blood at an adequate rate to meet tissue metabolic requirements. "GATM and STC1 have been among the top loci in genome-wide association studies of chronic kidney disease, and have also been implicated in heart failure." (PMID 23145134, 2012). "Previous studies have investigated the role of STC1 in the heart failure and cancer." (PMID 31379744, 2019). "STC1 was found to be differentially expressed in culprit coronary plaques of patients with AMI versus those with stable angina, and STC2 was shown to be an independent predictor of all-cause death and readmission due to heart failure in ST-segment elevation myocardial infarction." (PMID 34685725, 2021).
thyroid cancer (5 papers, 2017 to 2024). "The expression level of STC1 was higher in sarcoma, brain cancer, thyroid cancer, pancreatic cancer, and kidney cancer." (PMID 39201771, 2024).
colitis (4 papers, 2019 to 2025). Inflammation of the colon. "Meanwhile, PAR production was used to evaluate the degree of parthanatos, and it was markedly downregulated in Stc1INT‐KO+DSS mice, suggesting that Stc1 deficiency ameliorated parthanatos in DSS‐induced murine colitis." (PMID 38088577, 2024). "Importantly, adeno‐associated virus‐mediated restoration of Stc1 and Parp1 expression exacerbated dextran sodium sulfate‐induced colitis in Stc1INT‐KO mice, confirming the pathological synergy between STC1 and PARP1 in vivo." (PMID 40904702, 2025). "After restoring Stc1 and Parp1, Stc1INT‐KO mice with DSS‐induced colitis exhibited increased weight loss, shorter colons, higher DAI scores, more histological damage in the colonic epithelium, and higher histological scores." (PMID 38088577, 2024). "Evaluation of parthanatos severity and pro‐inflammatory cytokine expression shows that intestinal‐specific Stc1 knockout (Stc1INT‐KO) mice are resistant to dextran sulfate sodium (DSS)‐induced colitis and exhibit lower disease severity." (PMID 38088577, 2024). "Restoring Stc1 and Parp1 in vivo also led to more severe colonic mucosal damage during colonoscopy and higher endoscopic colitis scores." (PMID 38088577, 2024). "Results show that STC1 expression is markedly increased in the inflamed colonic mucosa of Crohn's disease (CD) patients and chemically‐induced mice colitis models." (PMID 38088577, 2024). "Herein, the function of STC1 in colitis and stress‐induced parthanatos, a newly identified type of programmed necrotic cell death dependent on the activation of poly‐ADP ribose polymerase‐1 (PARP1) is investigated." (PMID 38088577, 2024). "Finally, following restoration of Stc1 and Parp1 expression by adeno‐associated viruses, and overexpression of Stc1 and Parp1 aggravated DSS‐induced colitis in Stc1INT‐KO mice." (PMID 38088577, 2024). "In contrast, restoring Stc1 and Parp1 in vivo aggravated murine colitis." (PMID 38088577, 2024). "Similarly, STC1 protein levels were increased in the colonic tissues of both colitis models." (PMID 38088577, 2024). "STC1 may act as a player in the pathogenesis of colitis by inducing parthanatos." (PMID 38088577, 2024). "We further investigated whether restoration of Stc1 and Parp1 aggravated murine colitis." (PMID 38088577, 2024). "To recover Stc1 and Parp1 expression, we intraperitoneally injected Stc1INT‐KO mice with AAV and induced colitis with DSS three weeks later." (PMID 38088577, 2024). "Stc1 mRNA was upregulated in DSS‐ (7.88‐fold, p < 0.01) and TNBS‐induced murine colitis (2.64‐fold, p < 0.01)." (PMID 38088577, 2024). "Additional analyses showed that several factors, including chromosome 10 open reading frame 54, stanniocalcin-1, and TNF receptor superfamily member 11b were increased in MSCs after adding serum from DSS colitis mice." (PMID 31720090, 2019). "Also, by restoring Stc1 and Parp1 expression, the observed resistance to DSS‐induced colitis in Stc1INT‐KO mice was abolished." (PMID 38088577, 2024). "Hence, targeting STC1 and PARP1 might be a potential therapy for the alleviation of colitis." (PMID 38088577, 2024).
esophageal squamous cell carcinoma (4 papers, 2012 to 2022). Esophageal squamous cell carcinoma (ESCC) is a type of esophageal carcinoma (EC) that can affect any part of the esophagus, but is usually located in the upper or middle third. "The aim of this study was to examine STC-1 expression in peripheral blood (PB) and bone marrow (BM) of esophageal squamous cell carcinoma (ESCC) patients, and to evaluate its clinical significance." (PMID 22537917, 2012). "Quantitative reverse transcriptase-polymerase chain reaction and immunohistochemistry were performed to assess the expression of STC1 in the cancer cell line TE8 and esophageal cancer tissues from 229 esophageal squamous cell carcinomas (ESCC)." (PMID 22200953, 2012).
Hypercalcemia (4 papers, 2020 to 2025). An abnormally increased calcium concentration in the blood. "The rate of P reabsorption to adjust plasma P levels may involve Na/P co-transport activity through hormonal control such as PTH and vitamin D, but may also be effectively regulated by STC1, which enhances renal P reabsorption and prevents hypercalcemia." (PMID 39930376, 2025). "Other studies also demonstrated that overexpression of STC1 could protect from hypoxia- or hypercalcemia-induced neuron injury." (PMID 32318235, 2020). "STC1, a glycoprotein hormone first discovered in the corpuscles of Stannius, the endocrine glands on the kidney of bony fish, is a regulatory factor for calcium/phosphate homeostasis and protects the fish against toxic hypercalcemia." (PMID 32468698, 2020). "STC-1 was first described as a calcium regulatory protein in fish, being secreted from the corpuscles of Stannius to regulate calcium excretion at the gills and gut during hypercalcemia." (PMID 32365129, 2020).